RBP4 (retinol binding protein 4)
Diseases named in the same sentence as RBP4 in open-access papers (continued):
Sharing a sentence is not in itself a finding about the gene and the disease.
Obesity (255 papers, 2008 to 2026). Accumulation of substantial excess body fat. "Elevated circulating levels of retinol and its transport protein RBP4 have been linked to obesity, insulin resistance, type 2 diabetes, dyslipidemia, and increased cardiometabolic risk." (PMID 41535542, 2026). "Elevated serum levels of RBP4 have been associated with cardiovascular diseases, diabetes, and obesity, driving the development of RBP4-targeting drugs." (PMID 40444179, 2025). "Elevated levels of RBP4 are associated with obesity, type 2 mellitus diabetes, and cardiovascular diseases, making it a potential biomarker and therapeutic target." (PMID 40276651, 2025). "Circulating concentrations of RBP4 correlate with insulin resistance, obesity, and associated macrovascular complications." (PMID 40940776, 2025). "Consistent with animal studies, RBP4 concentrations in humans are significantly associated with obesity parameters—including BMI, body fat mass, waist and hip circumferences, and waist-to-hip ratio (WHR)—in both pediatric and adult populations." (PMID 41303567, 2025). "In obesity, elevated levels of RBP4 have been linked to the onset of metabolic diseases, including obesity, type 2 diabetes mellitus, and the metabolic syndrome." (PMID 40692090, 2025). "Genetic studies further support this association, with certain gain-of-function mutations in the RBP4 promoter linked to increased risk of obesity and type 2 diabetes." (PMID 41303567, 2025). "Chemerin and RBP4 are associated with obesity and metabolic syndrome markers such as BMI, body fat, leptin, lipid profile, blood glucose measurements, and fatty liver." (PMID 38892481, 2024). "RBP4, a novel adipocytokine associated with obesity, also demonstrates increased expression during adipocyte differentiation." (PMID 39238829, 2024). "It has been reported that the increase in RBP-4 levels was closely associated with obesity and impaired glucose tolerance." (PMID 37892122, 2023). "Several studies have discovered that elevated RBP4 levels are linked to obesity, metabolic syndrome, and an increased risk of cardiovascular disease, fatty liver, and polycystic ovary syndrome." (PMID 37512089, 2023). "Prior studies demonstrated an equivocal conclusion about the association between the level of retinol-binding protein 4 (RBP4)/visfatin and periodontitis patients with obesity." (PMID 38132460, 2023). "In human, single-nucleotide polymorphisms of RBP4 have been associated with obesity, diabetes, and, particularly, cardiovascular disease." (PMID 36750687, 2023). "With further rigorous longitudinal research, the exact causal relationships between RBP4/visfatin and patients affected by obesity and periodontitis can be determined." (PMID 38132460, 2023). "To sum up, as far as we are concerned, this was the first study to investigate the role of RBP4 and asprosin in periodontitis associated with obesity." (PMID 38069063, 2023). "Other obesity associated biomarkers worthy of prospective investigation into the effects of weight loss strategies on MetS-OA include RBP4, LOX-1 and the associated adipokines and inflammatory markers, as discussed." (PMID 36983885, 2023). "More recently, a study on women with obesity linked RBP4 with HGP relying on its stimulation on adipocyte lipolysis." (PMID 36091076, 2022). "As an adipokine, RBP4 has shown a close association with dyslipidemia, obesity, and vascular impairment." (PMID 35309061, 2022). "RBP4 has been proposed to be implicated in the pathophysiology of the metabolic consequences of obesity." (PMID 36686076, 2022). "The long-term effect of RBP4 on obesity, glucose, and other cardiometabolic risk needs to be further clarified." (PMID 35634496, 2022). "RBP4 mutations are associated with visual defects, obesity, cardiovascular disease and hypertriglyceridemia." (PMID 35496824, 2022).
Obesity (continued). "Elevated levels of RBP4 have been found in insulin-resistant mice and humans with obesity and T2DM, causing dysfunctions in the production of glucose transporter 4 (GLUT4) and consequently leading to a failure of glucose uptake from the blood." (PMID 36551028, 2022). "Some gain-of-function mutations on RBP4 promoter were reported to be associated with a higher risk of developing obesity or type 2 diabetes while a non-coding mutation in RBP4 promoter is associated with dyslipidemia." (PMID 34638803, 2021). "Previous works had found that RBP4 is associated with IR in various conditions, such as type 2 diabetes and obesity." (PMID 34177800, 2021). "On the other hand, certain studies demonstrate increased RBP4 concentrations among individuals with obesity, as well as the association between RBP4 and BMI." (PMID 32718041, 2020). "Retinol-binding protein 4 is one of the adipokines potentially associated with an increased risk of developing cardiovascular disease, particularly among patients with obesity." (PMID 32718041, 2020). "Retinol-binding protein (RBP4) is another adipokine that is elevated in obesity and causes insulin resistance." (PMID 33182462, 2020). "Because of the close correlation between obesity, MetS and OA, we analysed here, for the first time, the potential associations of RBP4 into the pathogenesis of OA." (PMID 32095874, 2020). "In humans, the increased serum RBP4 levels were also associated with obesity and insulin resistance." (PMID 31147589, 2019). "The retinol-binding protein 4 (RBP4) is a circulating retinol transporter that has been linked with cardiometabolic markers in inflammatory chronic diseases, including obesity, T2DM, metabolic syndrome, and atherosclerosis." (PMID 31666083, 2019). "Levels of circulating RBP4 have been linked to metabolic diseases such as insulin resistance, obesity, metabolic syndrome, diabetes, and fatty liver disease, representing chronic inflammatory diseases." (PMID 31569348, 2019). "Carriers of the PNPLA3-I148M allele with either NAFLD or obesity alone have reduced fasting circulating retinol and RBP4 levels." (PMID 29286303, 2017). "More recent data indicate that elevated serum RBP4 levels are specifically associated with obesity- and T2D-associated reduced kidney function, suggesting that impaired renal clearance of RBP4 is an important contributing factor." (PMID 29286303, 2017). "Although the precise mechanisms are still unclear, elevated PTX-3, RBP-4, IL-33, irisin and decreased adiponectin levels increase the risk of obesity-related metabolic disorders." (PMID 28977161, 2017). "Obesity is known to increase serum RBP4 levels, and in a recent study high serum RBP4 levels were correlated to increased colon adenoma risk." (PMID 28689994, 2017). "In the current study, we found that serum RBP4 levels were inversely associated with E2 levels in a cohort of Chinese women patients with obesity." (PMID 26960804, 2016). "To investigate the participation of sex hormones in the association of RBP4 and obesity in humans, we measured serum RBP4, BMI, and sex hormones in 87 women from the outpatient." (PMID 26960804, 2016). "CST also effectively decreased the expression level of gene encoding obesity-promoting adipokine (retinol-binding protein-4) and increased the mRNA level of obesity-suppressing adipokine (adiponectin) in visceral adipose tissue (VAT)." (PMID 27845741, 2016). "This decrease in circulating RBP4 levels had been proposed to be the mechanism that FEN treatment led to prevention of insulin resistance associated with high-fat diet (HFD) induced obesity." (PMID 26592777, 2016). "In epidemiological studies, increased serum RBP4 levels have been linked to obesity and increased serum TG levels." (PMID 24475021, 2014). "Increased serum RBP4 levels in humans are associated with obesity, metabolic syndrome, type 2 diabetes and cardiovascular disease." (PMID 24475021, 2014).
Obesity (continued). "The lipocalin family proteins, including lipocalin-2 and retinol-binding protein 4 (RBP4), are adipokines closely associated with obesity-related metabolic disorders." (PMID 23799122, 2013). "Obesity-related adipose tissue inflammation was linked to increased adipose tissue RBP4 expression, which positively correlated with expression of inflammatory markers in human adipose tissue." (PMID 23460908, 2013). "In population-based studies, RBP4 levels were positively associated with the obesity index, high blood pressure, and unfavorable lipid profiles." (PMID 23970879, 2013). "RBP4 levels are closely associated with obesity, particularly visceral adiposity in mice and humans." (PMID 23970879, 2013). "Overweight and obesity are associated with a different secretion rate of several adipocytokines, such as reduced adiponectin and increased retinol-binding protein 4 (RBP4), adipocyte fatty acid binding protein (aFABP), and visfatin." (PMID 21869928, 2012). "In various chronic diseases associated with obesity RBP4 is produced largely by mature adipocytes and activated macrophages in the adipose tissue." (PMID 23119072, 2012). "This association of RBP4 with body fat has been extended to various obesity-associated metabolic and cardiovascular disorders." (PMID 23119072, 2012). "Among these, the lipocalin family proteins, FABP4, LCN2 and RBP4, have been identified as adipokines associated with obesity, type 2 diabetes and metabolic syndrome." (PMID 23119072, 2012). "Importantly, RBP4 polymorphisms are linked to coronary artery disease, cardiovascular disease risk factors, and obesity." (PMID 38673873, 2024). "However, RBP4 also exhibits many cardiometabolic properties, being associated with obesity, insulin resistance, diabetes mellitus type 2 and related cardiometabolic complications." (PMID 39139157, 2024). "Furthermore, we observed a positive correlation between the reduction of glucose and proteins associated with alleviating obesity and type 2 diabetes, such as Insig2, Dgat2 and Rbp4." (PMID 38188177, 2024). "With more rigorous longitudinal research, the exact causations between RBP4/visfatin and the patients affected by obesity and periodontitis could be disentangled." (PMID 38132460, 2023). "Furthermore, to explore the association between RBP4/visfatin and periodontal and obesity parameters, Fisher’s Z transformation was selected to calculate the given Pearson correlation coefficient." (PMID 38132460, 2023). "The results of this study showed that circulating irisin, adiponectin, and RBP-4 levels may be new biomarkers in addition to risk factors such as DM, obesity, and HT." (PMID 37892122, 2023). "Retinol binding protein 4 (RBP-4) is positively associated with obesity." (PMID 37048738, 2023). "Furthermore, RBP4 has strong associations with obesity and periodontitis due to its specific relationship with inflammation and oxidative stress." (PMID 38132460, 2023). "However, the prior studies demonstrated a rather equivocal conclusion about the association between the level of RBP4/visfatin and periodontitis patients with obesity." (PMID 38132460, 2023). "Among these, retinol-binding protein 4 (RBP4) and asprosin are two novel adipokines with ill-defined functions in the process of obesity and periodontitis, while associations have been discovered between these two adipokines and other metabolic diseases or periodontitis." (PMID 38069063, 2023). "RBP4 levels are elevated in obesity and are positively associated with BMI." (PMID 36686076, 2022). "RBP4 levels are elevated in obesity and are positively associated with BMI and WHR." (PMID 31956345, 2020). "Despite different data, there is still a strong association between RBP4 and obesity." (PMID 32718041, 2020). "However, few studies involved studying the association of RBP4 levels with thyroid function in obesity." (PMID 31956345, 2020).
Obesity (continued). "In our study, RBP4 levels were also significantly higher in obese patients than healthy controls with normal BMI and RBP4 levels were also significantly associated with BMI in obesity." (PMID 31956345, 2020). "However, increased levels of other adipokines, such as leptin, omentin, vaspin, resistin, and retinol binding protein 4 (RBP4) are associated with the development of obesity-related metabolic disturbances." (PMID 31920976, 2019). "For example, in diabetes and obesity, there is a significant association between parental history of obesity and diabetes and levels of serum fatty acid-binding protein 4, retinol-binding protein 4, and adiponectin, favouring obesity the risk developing of these disorders in offspring." (PMID 31582905, 2019). "Increasing numbers of clinical studies have shown that increased circulating RBP4 are not only correlated with established cardiovascular risk factors such as obesity and dyslipidemia, but also correlated with the prevalence of atherosclerotic diseases and CAD." (PMID 31278889, 2019). "Furthermore, our study demonstrated a significant association between the serum RBP4 levels and metabolic risk factors, including IR, dyslipidemia and obesity, in this cohort." (PMID 28332619, 2017). "In conclusion, RBP4 could be a marker of obesity-related risk factors, and it is negatively related to estrogen, restricted to obese individuals." (PMID 26960804, 2016). "Therefore, the major aim of the present study is to evaluate the association between RBP4 levels, obesity, sex hormones, as well as other metabolic parameters in Chinese women." (PMID 26960804, 2016). "Treatment of obesity and/or diabetes through weight loss, exercise, lifestyle intervention, bariatric surgery, or thiazolidinedione treatment lowers serum RBP4 levels." (PMID 25918733, 2015). "High-amount SSB intake (>750 ml/day) was related to high weight and waist and hip circumferences (P<0.05), and increased SSB intake was linked to increased BMI values; serum UA, TG and RBP4 levels; overweight/obesity percentages and hyperuricemia (P for trend <0.05)." (PMID 24475021, 2014). "Our results support the previously proposed hypothesis that high fructose consumption has a significant effect on the association of RBP4 with obesity and TG." (PMID 24475021, 2014). "Thus, RBP4 contributes to the development of obesity and its associated diseases, including NAFLD." (PMID 38672227, 2024). "In addition, the administration of caffeine in mice resulted in decreased or increased levels of certain proteins, such as Insig2, Rbp4, and Igfbp1, which have been associated with improved obesity, type 2 diabetes mellitus (T2DM), and cardiovascular pathologies." (PMID 38188177, 2024). "However, it is noteworthy that obesity is a major risk factor for OA, and OA is increasingly regarded as the fifth clinical feature of metabolic syndrome, which makes the adipokine RBP4 a potential novel factor linking the metabolic state, inflammation and articular degradation in OA." (PMID 32095874, 2020). "In addition to the classical adipocytokines, several novel adipocytokines, namely omentin-1, vaspin, and retinol binding protein-4 (RBP-4), have been discovered recently, and their associations with obesity-related metabolic diseases have become interesting topics in obesity studies." (PMID 28658347, 2017). "In metabolic diseases such as obesity and type 2 diabetes, elevated RBP4 levels engage endothelial STRA6, initiating a signaling cascade independent of retinol nuclear activity." (PMID 41782879, 2026). "Lcn2 deficiency attenuated the effects of atRA on obesity, lipid metabolism, and thermogenesis, whereas retinoid transport was disrupted through the stimulation by retinoic acid 6 (STRA6) and RBP4 pathways." (PMID 41535542, 2026). "Positive correlations have also been reported between RBP4 and visceral adipose tissue (VAT) volume, associated with increased cardiometabolic risk in obesity." (PMID 41303567, 2025).
Obesity (continued). "High IL-6 expression correlated with age and obesity measures, while RBP4 expression showed significant associations with pT stage, lymph node involvement, TNM stage, and obesity-related parameters." (PMID 41007818, 2025). "RBP4 levels are elevated in obesity and contribute to macrophage activation and pro-inflammatory cytokine release via TLR and JNK pathways." (PMID 41157128, 2025). "The effect of holo-RBP4 on latent HIV reservoirs in individuals with obesity also requires further study." (PMID 41038866, 2025). "The progression of obesity often leads to elevated secretion of Rbp4 by adipocytes, impairing insulin sensitivity and accelerating lipolysis in adipose tissue." (PMID 38474824, 2024). "It has also been described that increased levels of RBP4 are related to pathological conditions (diabetes, obesity, heart disease)." (PMID 39795999, 2024). "Meanwhile, the generation of adiponectin, leptin, visfatin, retinol binding protein-4 and resistin become irregularly and the production of free fatty acids begins to increase, then the obesity-related syndromes occurred and worsen." (PMID 38475734, 2024). "In 2005, Kahn’s group published a landmark paper describing the contribution of RBP4 to obesity and diabetes." (PMID 39624361, 2024). "On the other hand, serum retinol-binding protein-4 is positively associated with CVD, T2DM, and obesity, potentially contributing to the development of obesity-related co-morbidities." (PMID 39771044, 2024). "Retinol-binding protein 4 (RBP4), vitamin A, and vitamin E are the main subjects of modern obesity research." (PMID 39434876, 2024). "RBP4 is primarily produced by the liver and adipose tissue, and its expression is elevated in insulin-resistant mice and humans with obesity and type 2 diabetes." (PMID 38672227, 2024). "In patients with obesity, RBP-4 promotes oxidative stress by decreasing endothelial mitochondrial function." (PMID 37883447, 2023). "Some adipokines that are positively correlated with obesity (visfatin, osteopontin, apelin, retinol-binding protein 4, galectin) exert pro-carcinogenic effects." (PMID 37048738, 2023). "After three months of NSPT, serum (MD = -0.54, CI = -0.62 – -0.46), and GCF (MD = -2.70, CI = -4.77 – -0.63) levels of IL-6, along with the serum RBP4 (MD = -0.39, CI = -0.68–0.10) decreased in periodontitis individuals with obesity." (PMID 37798684, 2023). "To further investigate the role of RBP4 and visfatin as the path mechanistic link between periodontitis and obesity, we, thereby, carried out this systematic review and meta-analysis." (PMID 38132460, 2023). "Another study positively correlated obesity and type II diabetes mellitus with the inhibition of insulin signalling and upregulation of RBP4." (PMID 36776154, 2023). "Using RBP4 as a measure of status can thus lead to overestimation of vitamin A status in individuals with overweight and obesity." (PMID 38686175, 2023). "At the same time, retinol binding protein 4 (RBP4) is highly expressed in adipose tissue and found to be higher in subjects with obesity and T2D." (PMID 37512089, 2023). "For example, retinol binding protein 4 (RBP4), which is a novel adipokine, is mainly secreted by adipocytes and is related to obesity." (PMID 37252399, 2023). "The aim of our study (Prospero ID: CRD42023469058) was to systematically review the available articles linking the biofluid levels of RBP4/visfatin to the comorbidity of periodontitis and obesity." (PMID 38132460, 2023). "Effective nonsurgical periodontal therapy has been shown to reduce serum RBP4 levels at a 3-month follow-up timepoint in patients with both obesity and periodontitis." (PMID 38132460, 2023). "Retinol-binding protein 4 (RET4) is a recently identified adipokine that is elevated in patients with obesity or type 2 diabetes." (PMID 36835577, 2023).